TRPC5 (transient receptor potential cation channel subfamily C member 5)
Description:
Forms a receptor-activated non-selective calcium permeant cation channel. Mediates calcium-dependent phosphatidylserine externalization and apoptosis in neurons via its association with PLSCR1 (By similarity). Acts on distinct neuronal populations in the hypothalamus to regulate innate behaviors including feeding, anxiety (flight/fight/fear), socialization, and maternal care (By similarity).
Synonyms: TRP5; PPP1R159
Tractability: Small molecule: a structure with a bound ligand is known; a high-quality ligand is known; it belongs to a druggable protein family. Antibody: UniProt places it where antibodies can reach, with high confidence; its Gene Ontology location is reachable by antibodies, with high confidence; UniProt predicts a signal peptide or a membrane-spanning region. PROTAC: a small molecule that binds it is known.
Target class: Voltage-gated ion channel; Ion channel; Transient receptor potential channel
Chemical probes: Englerin-A
Gene: Protein-coding gene on chromosome X (111,768,011 to 112,082,776, reverse strand). Ensembl gene ENSG00000072315.
Subcellular location: Cell membrane
Pathways (Reactome):
Developmental Biology: Role of second messengers in netrin-1 signaling
Transport of small molecules: TRP channels
Gene Ontology:
Molecular function: calcium channel activity; protein binding; inositol 1,4,5 trisphosphate binding; store-operated calcium channel activity; actin binding; actinin binding; ATPase binding; clathrin binding; monoatomic ion channel activity
Biological process: calcium ion transmembrane transport; calcium ion transport; nervous system development; neuron apoptotic process; phosphatidylserine exposure on apoptotic cell surface; regulation of cytosolic calcium ion concentration; monoatomic ion transport; negative regulation of dendrite morphogenesis; neuron differentiation; positive regulation of axon extension; positive regulation of cell population proliferation; positive regulation of cytosolic calcium ion concentration; positive regulation of neuron differentiation; regulation of membrane hyperpolarization; transmembrane transport
Cellular component: calcium channel complex; cation channel complex; plasma membrane; dendrite; growth cone; membrane; neuronal cell body; presynapse
Homologues: Orthologues: chimpanzee TRPC5 (100% identical), macaque TRPC5 (99% identical), pig TRPC5 (99% identical), rabbit TRPC5 (99% identical), dog TRPC5 (98% identical), guinea pig TRPC5 (98% identical), rat Trpc5 (97% identical), mouse Trpc5 (97% identical), tropical clawed frog trpc5 (83% identical), zebrafish trpc5b (72% identical), zebrafish trpc5a (51% identical), Drosophila melanogaster Trpgamma (41% identical), and 3 more. Paralogues in human: TRPC4 (64% identical), TRPC1 (38% identical), TRPC7 (33% identical), TRPC3 (33% identical), TRPC6 (33% identical).
Diseases named in the same sentence as TRPC5 in open-access papers:
TRPC5 is named in the same sentence as 114 diseases in open-access papers, as found by Europe PMC text mining. Sharing a sentence is not in itself a finding about the gene and the disease. The quoted sentences say what the papers report.
breast carcinoma (43 papers, 2016 to 2025). "Gd3+ is a known activator of the TRPC5 channel that is implicated in breast cancer’s resistance to chemotherapy." (PMID 37174704, 2023). "Upregulation of TRPC5 activity has been recently implicated in conferring chemoresistance to breast cancer cells." (PMID 37174704, 2023). "Further, the level of circulating EV-TrpC5 had a significant positive association with TRPC5 protein level in tissues of patients with advanced breast cancer prior to chemotherapy, suggesting a role for circulating EVs in evaluation of chemoresistance." (PMID 30682793, 2019). "Induction of this protein has been associated with upregulation of the Ca2+-permeable channel TRPC5 in adriamycin-resistant breast cancer cell lines." (PMID 29636894, 2018). "The increased TRPC5 channel activity in breast cancer and in colorectal cancer cells caused an increased expression of the ABC transporter P-glycoprotein (MDR1)." (PMID 30463370, 2018). "It is also known that TRPC5 is associated with breast cancer cells and colorectal cancer cells." (PMID 40723382, 2025). "Escaping Gd3+ may tonically potentiate the TRPC5 signaling cascade linked to conferring chemoresistance to breast cancer cells." (PMID 37174704, 2023). "Targeting TRPC5 and its associated pathways could be a potential therapeutic strategy to overcome chemoresistance in breast cancer." (PMID 37755210, 2023). "In addition, TRPC5 mediates cytoprotective autophagy through the CaMKKβ/AMPKα/mTOR pathway, causing drug resistance in breast cancer cells." (PMID 35573736, 2022). "It has recently been shown that endothelial TRPC5 could underlie the development of chemoresistance to anticancer drugs in both breast cancer and colorectal carcinoma." (PMID 29324706, 2018). "In breast cancer, doxorubicin up-regulates TRPC5 expression and promotes autophagy through the CaMKKβ/AMPKα/mTOR signaling pathway." (PMID 39744692, 2025). "TRPC5 promotes chemoresistance in breast cancer through the release of exosomes enriched with TRPC5 protein and associated drug-efflux machinery." (PMID 40813985, 2025). "For instance, TRPC5-mediated Ca2+ entry was reported to stimulate P-glycoprotein production in adriamycin-resistant MCF-7/ADM breast cancer cells via NFATc3." (PMID 39436410, 2025). "Increased abundance of the Transient Receptor Potential Channel 5 (TrpC5) in EVs was observed in adriamycin-resistant human breast cancer cells (MCF-7/ADM) and was correlated with EV formation; additionally, adriamycin was found in EVs." (PMID 37629204, 2023). "Considering the role of TRPC5 in breast cancer chemoresistance and the repeated use of Gd-DTPA in cancer patients, we investigated the effects of long-term Gd-DTPA or GDD treatment on the expression of TRPC5 in MCF-7, SK-BR-3, and MCF-7/ADM cells." (PMID 37174704, 2023). "Treatment with Gd-DTPA or GDD significantly increased TRPC5 expression and decreased the accumulation of ADM in the nuclei of MCF-7 and SK-BR-3 cells, increasing the risk ofchemoresistance in the breast cancer cells." (PMID 37174704, 2023). "It is a more complex process which also involves calcium influx through TRPC5 itself, leading to a calcium-dependent acceleration of the breast cancer cell cycle." (PMID 37174704, 2023). "Adriamycin-resistant breast cancer cell-derived EVs were shown to carry transient receptor potential cation channel subfamily C member 5 (TrpC5) and to transfer of EV." (PMID 37371477, 2023). "Remarkably, four weeks of treatment with Gd-DTPA or GDD significantly increased TRPC5 expression in the studied breast cancer cell lines." (PMID 37174704, 2023). "For instance, some researchers have shown that transient receptor potential channel 5 (TrpC-5)-containing EVs in breast cancer and P-glycoprotein (P-gp)-containing microvesicles in ovarian cancer are responsible for chemotherapeutic resistance." (PMID 37754253, 2023).
breast carcinoma (continued). "Further studies have found that TRPC5 levels in plasma EVs are significantly correlated with TRPC5 levels in breast cancer tissues and chemotherapy response." (PMID 37534210, 2023). "It was also shown that chemoresistant breast cancer cells overexpressing the TRPC5 transfer channel units to chemo sensitive recipient cells via extracellular vesicles leads to the development of TRPC5-mediated chemoresistance in these cells." (PMID 37755210, 2023). "It has been shown that chemosensitive breast cancer cells can acquire a chemoresistant phenotype when exposed to extracellular vesicles (eVs) expressing TRPC5." (PMID 37755210, 2023). "It is conceivable that the observed proliferative effect arises through the transfer and incorporation of functional TRPC3 channels into the membrane of recipient cells—as reported for the EV‐mediated transfer of TRPC5 from chemoresistant breast cancer cells." (PMID 38938673, 2023). "In a similar manner, TRPC5 channel expression is increased in breast cancer cell lines together with P-glycoprotein (P-gp), another pump overexpressed by cancer cells to remove cytotoxic drugs." (PMID 37892239, 2023). "In human breast cancer cells, the high expression of TRPC5, and consequently, the high Ca2+ influx via the channel activated the transcription factor NFATC3 (Nuclear Factor of Activated T Cells, Cytoplasmic 3), which triggers p-gp transcription." (PMID 37755210, 2023). "It was shown that Rac1, which is an actin cytoskeleton regulator and which is found to be overexpressed in breast tumor cells, is activated by a TRPC5-mediated Ca2+ influx, which promotes breast cancer cells’ migration." (PMID 37755210, 2023). "Specifically, chemo-resistant breast cancer cells can release EVs containing TRPC5, which is then delivered to chemo-sensitive cells, subsequently leading to acquired chemoresistance." (PMID 37534210, 2023). "Overall, TRPC5 plays a significant role in breast cancer drug resistance by regulating p-gp expression, promoting autophagy, and facilitating the transfer of chemoresistance to neighboring cells via eVs." (PMID 37755210, 2023). "Overexpression of TRPC5 induces chemoresistance by up-regulating of P-glycoprotein (P-gp) and hypoxia-inducible factor-1α in chemoresistant breast cancer cells." (PMID 35573736, 2022). "Transient receptor potential channel 5 (TrpC5), a Ca2+-permeable cation channel, promotes exosome secretion, through which chemoresistance is transferred to recipient cells in breast cancer." (PMID 36320056, 2022). "In breast cancer, the transient receptor potential channel 5 (TRPC5) protein carried by TMV was demonstrated to regulate the expression of P-gp and promote tumor drug resistance." (PMID 35890175, 2022). "Ca2+ influx via TRPC5 enhances the release of these exosomes, which can enter other breast cancer cells and confer resistance." (PMID 36158191, 2022). "Accordingly, breast cancer patients exhibit markedly increased levels of TRPC5 and the autophagy marker LC3 after chemotherapy." (PMID 36158191, 2022). "Breast cancer cells resistant to doxorubicin express high levels of TRPC5, which enhances the expression of P-glycoprotein via the Ca2+-dependent transcription factor NFATc3." (PMID 36158191, 2022). "For instance, the transient receptor potential channel 5 (TrpC5) is responsible for increased levels of EV formation and secretion in doxorubicin-resistant breast cancer cells." (PMID 33920605, 2021). "TRPC5 expression in breast cancer tissues and patient response to chemotherapy are significantly correlated with the level of cirExo-TRPC5 in peripheral blood." (PMID 34631581, 2021). "Further studies show that TRPC5 also mediates autophagy by the CaMKKβ/AMPKα/mTOR pathway and therefore enhances the adriamycin resistance in breast cancers." (PMID 32211326, 2020).
breast carcinoma (continued). "When breast cancer cells or patients are treated with adriamycin, TRPC5 is upregulated in extracellular vesicles, which is believed to be responsible for the drug resistance." (PMID 32211326, 2020). "Autophagy can be also mediated by TRPC5 and promotes drug resistance via CaMKKβ/AMPKα/mTOR pathway in breast cancer cells." (PMID 30884858, 2019). "Transient receptor potential channel 5 (TrpC5) has also been shown to accumulate in EVs released by drug resistant breast cancer cells, resulting in sequestration of chemotherapeutic drugs." (PMID 30682793, 2019). "Accordingly, a blocking TRPC5 antibody reduced P-gp expression, retarded cancer growth and boosted paclitaxel-induced tumor regression in chemoresistant breast cancer in vivo." (PMID 29324706, 2018). "Recently, up-regulation of TRPC5 expression was found to be associated with chemoresistance in human CRC and breast cancer." (PMID 29463225, 2018). "Here, we demonstrate that adriamycin up-regulates the both levels of TRPC5 and autophagy, and the increase in autophagy is mediated by TRPC5 in breast cancer cells." (PMID 28600513, 2017). "In order to investigate the clinical potential of TRPC5 in the induction of autophagy in breast cancer, we analyzed breast cancer tissue from 31 paired patients with or without anthracycline-taxane-based chemotherapy." (PMID 28600513, 2017). "Here, we showed that TRPC5-regulated autophagy is an important contributor to the development and maintenance of drug resistance in breast cancer." (PMID 28600513, 2017). "Taken together, our results suggested that TRPC5 and autophagy are both up-regulated breast carcinoma cells during ADM exposure." (PMID 28600513, 2017). "Together, our data suggested that chemotherapy-induced autophagy is regulated by TRPC5 in breast carcinoma cells." (PMID 28600513, 2017). "In agreement with the previous findings that inhibition of mTOR induces autophagy, our data showed that the autophagy induced by TRPC5 is dependent on mTOR inhibition in breast cancer cells undergoing chemotherapy." (PMID 28600513, 2017). "LC3 puncta formation was also significantly enhanced by TRPC5 overexpression in breast cancer cells under chemotherapy." (PMID 28600513, 2017). "Here, we found that ADM exposure enhanced the expression of TRPC5 in drug sensitive breast cancer cells (MCF-7, T47D and MDA-MB 231 cells)." (PMID 28600513, 2017). "In conclusion, our findings showed that TRPC5-induced autophagy counteracts the antiproliferative effects of ADM via the CaMKKβ/AMPKα/mTOR pathway in breast cancer cells." (PMID 28600513, 2017). "Our current findings reveal a novel role of TRPC5 as an inducer of autophagy, and suggest a novel mechanism of drug resistance in chemotherapy for breast cancer." (PMID 28600513, 2017). "TRPC5 expression is also related to chemotherapy-resistant breast cancer cells and might be a marker for chemoresistance in breast cancer cells and colorectal cancer cells." (PMID 40723382, 2025). "Moreover, TRPC5 channel expression was increased together with P-gp in breast cancer cell lines, and inhibition of TRPC5 reduced P-gp level and reversed cell drug resistance." (PMID 38505262, 2024). "Moreover, elevated TRPC5 levels in plasma EVs after chemotherapy have been reported to strongly predict acquired chemoresistance in patients with breast cancer." (PMID 37534210, 2023). "Additionally, the authors demonstrated that TRPC5 plays a key role during extracellular vesicle (EV) formation and release from breast cancer cells." (PMID 37174704, 2023). "Recently, the role of TRPC5 in breast cancer cell resistance to chemotherapy has been discovered." (PMID 37174704, 2023). "Notably, upregulation of TRPC5 protein expression is crucial for P-gp induction and the development of chemoresistance in breast cancer cells." (PMID 37174704, 2023).
breast carcinoma (continued). "In addition, the positive correlation between the expression of the transient receptor potential channel 5 (TRPC5) and autophagic states is associated with the CaMKKβ/AMPKα/mTOR/p70S6K signaling pathways in adriamycin-resistant breast cancer cells." (PMID 36677797, 2023). "However, there is a possibility that the escape of Gd3+ from its chelating cages of the clinically used formulations utilized for contrast-enhanced MRI would modulate TRPC5 activity in breast cancer cells to promote breast cancer cell chemoresistance." (PMID 37174704, 2023). "Moreover, TRPC5 has been identified as a potential exosome biomarker in breast cancer chemoresistance, affecting the neighboring cells." (PMID 37755210, 2023). "In this study, we tested the hypothesis that long-term treatment with GBCAs would affect TRPC5 expression and/or modulate breast cancer cell survival by increasing ADM resistance." (PMID 37174704, 2023). "Moreover, TRPC5 is a potential biomarker in breast cancer chemoresistance since its overexpression in cancer cells was correlated to Adriamycin resistance." (PMID 37755210, 2023). "It has also been shown that TRPC5 is highly expressed in human breast cancer after long-term chemotherapy treatment, and its presence has been correlated with an increase in the transcription of vascular endothelial growth factor, which, in turn, stimulates tumor angiogenesis." (PMID 37892239, 2023). "This pathway may participate in the translocation and release of TRPC5 exosomes in breast cancer, however further investigation is required." (PMID 36158191, 2022). "The human oestrogen receptor positive (ER+) MCF-7 breast cancer cell line feature high levels of TRPC5 expression making them resistant to doxorubicin cytotoxic effect, and TRPC5 silencing can increase sensitivity to doxorubicin by reducing (MDR)ATPase 1 expression." (PMID 35163823, 2022). "TRPC5-mediated Ca2+ entry stimulates P-gp overproduction through NFATc3 in breast cancer cells." (PMID 35573736, 2022). "In long-term adriamycin-treated breast cancer cells, TRPC5-mediated Ca2+ influx promoted HIF-1α translocation in the nucleus and therefore the downstream transcription of HIF-1α-regulated VEGF expression, highlighting its contribution to promoting breast cancer angiogenesis." (PMID 35806388, 2022). "Interestingly, breast cancer patients contain circulating exosomes with TRPC5 in their peripheral blood." (PMID 36158191, 2022). "TRPC5 also plays an important role in breast cancer chemoresistance." (PMID 36158191, 2022). "The role of TrpC5 is also clinically relevant; for example, in breast cancer patients undergoing treatment with doxorubicin, TrpC5 expression levels are significantly higher in those with progressive disease compared to patients with partial or complete response." (PMID 33920605, 2021). "In addition, TRPC5 is also upregulated in breast cancers and mediates angiogenesis during tumor progression, which is another important aspect that TRPC5 promotes breast cancers metastasis." (PMID 32211326, 2020). "TRPC5 is another TRPC that has been well-addressed in breast cancers progression." (PMID 32211326, 2020). "Furthermore, elevated TRPC5 in circulating exosomes negatively correlates with chemotherapy outcome in colorectal and breast cancer patients, suggesting that increased TRPC5 is associated with chemoresistance." (PMID 32575381, 2020). "TRPC5 can confer chemoresistance to anticancer drugs in breast cancer." (PMID 30884858, 2019). "Indeed, in the adriamycin-resistant breast cancer study, suppressing the activity of pro-oncotic TRPC5 reduced MDR1 induction and reversed adriamycin resistance both in vitro and in vivo." (PMID 29636894, 2018). "Future work will have to assess whether, besides conferring B-TECs with the resistance to chemotherapeutic drugs, TRPC5 up-regulation accelerates breast cancer angiogenesis." (PMID 29324706, 2018).